LRP6 (LDL receptor related protein 6)
Diseases named in the same sentence as LRP6 in open-access papers (continued):
Sharing a sentence is not in itself a finding about the gene and the disease.
osteoporosis (26 papers, 2009 to 2025). A condition of reduced bone mass, with decreased cortical thickness and a decrease in the number and size of the trabeculae of cancellous bone (but normal chemical composition), resulting in increased fracture incidence. "Future studies can delve into the molecular mechanisms of LRP5 and LRP6 in skeletal cell biology and further reveal their association with bone diseases such as fracture healing and osteoporosis." (PMID 39468464, 2024). "Based on the role of LRP6 in WNT signaling, it was suggested that the observed osteoporosis phenotype was also caused by the mutation in LRP6." (PMID 32328030, 2020). "In humans, LDL receptor-related protein 6 (LRP6) mutation was related to high serum LDL-C levels complicated by severe osteoporosis." (PMID 30459714, 2018). "The finding offers new understanding on the role of LRP6 in the pathogenesis of atherosclerosis and associated osteoporosis." (PMID 30038821, 2018). "Furthermore, LRP6 is associated with complex diseases, such as hypercholesterolemia, atherosclerosis, Alzheimer’s disease, osteoporosis, heart diseases, diabetes, and cancers." (PMID 35052459, 2022). "Mutations in Lrp6 have been associated with diseases such as Alzheimer's, cancer, and osteoporosis." (PMID 34712254, 2021). "Only one or two disease-causing LRP6 missense mutations have been found so far, including the one associated with coronary artery disease and osteoporosis, reflecting the likelihood that a severe or complete loss of function of LRP6 is incompatible with embryogenesis." (PMID 21887268, 2011). "Given that LRP6 is a positive regulator for osteoblastic bone formation, and that patients with autosomal dominant LRP6 mutations developed simultaneous early onset atherosclerosis and osteoporosis, it is possible that oxPLs directly target LRP6 in bone cells during hyperlipidemia/atherosclerosis." (PMID 30038821, 2018). "Mutation of LRP6 in humans were shown to cause both early-onset cardiovascular diseases and severe osteoporosis complicated by high serum low-density lipoprotein cholesterol (LDL-C) levels, suggesting that this mutation could cause bone fragility, as well as atherosclerosis." (PMID 27738662, 2016). "Of interest, LRP6 has been considered as an important therapeutic target for multiple diseases, particularly for osteoporosis." (PMID 35414004, 2022). "Herein, we sought to probe the regulatory role of HuR in the LRP6 gene and their interaction in the progression of osteoporosis." (PMID 35414004, 2022). "Specifically, HuR can bind to the 3’UTR of LRP6 mRNA, and consequently promoted the stability of LRP6 mRNA and its translation, thus inducing osteogenic differentiation and arresting the development of osteoporosis." (PMID 35414004, 2022). "In conclusion, HuR can promote the expression of LRP6 and thereby activate the downstream Wnt pathway, facilitating osteogenic differentiation, thus relieving osteoporosis progression." (PMID 35414004, 2022). "The fact that endocytosis inhibitor or Mesd overexpression antagonized these adverse effects of oxPLs further supports this concept and implies that manipulation of cell surface LRP6 is a potential strategy for the treatment of osteoporosis." (PMID 30038821, 2018). "Taken together, this study represents the first evidence for the post-transcriptional regulation of LRP6 by HuR in osteoblasts and may have importance in regulating osteoporosis progression." (PMID 35414004, 2022). "Additionally, the present study confirmed that the therapeutic effect of HuR on the osteoporosis was achieved by the upregulation of LRP6." (PMID 35414004, 2022). "Both in vitro and in vivo findings in the current study suggested that RNA-binding protein HuR could potentially promote osteogenic differentiation and thus alleviated osteoporosis progression by promoting LRP6 expression at protein level." (PMID 35414004, 2022).
osteoporosis (continued). "Candidate osteoporosis genes commonly shared with AD and PD may include the LRP5 and LRP6 genes, which are partially affected by LRRK2 mutations, in the canonical Wnt signaling pathway." (PMID 34955816, 2021). "Thus, alterations in the LRP6 gene might affect Wnt/β-catenin signaling and lead to several human diseases including osteoporosis, Alzheimer's disease, coronary artery disease, and metabolic disease." (PMID 35187114, 2021). "A missense mutation in LRP6 (as a co-receptor for WNT signalling proteins for the canonical WNT signalling pathway) that resulted in impaired WNT signalling was reported in a family with autosomal dominant early coronary artery disease, metabolic risk factors and osteoporosis." (PMID 31480018, 2019). "Emerging evidence has correlated the human antigen R (HuR) with the low-density lipoprotein receptor-related protein 6 (LRP6) gene, an important therapeutic target for osteoporosis." (PMID 35414004, 2022). "While LRP6 is essential for embryogenesis, both LRP5 and LRP6 play critical roles for skeletal remodeling, osteoporosis pathogenesis and cancer formation, making LRP5 and LRP6 key therapeutic targets for cancer and disease treatment." (PMID 21887268, 2011). "Lrp5−/− mice and heterozygous Lrp6+/− mice are viable and exhibit OPPG/osteoporosis phenotypes demonstrating their overlapping functions in at least some aspects of bone development/homeostasis." (PMID 21887268, 2011).
colorectal cancer (24 papers, 2011 to 2024). A primary or metastatic malignant neoplasm that affects the colon or rectum. "From these targets, LRP6 is involved in the Wnt-signalling pathway, which is prominent in colorectal cancer, but has also been implicated in ovarian cancer." (PMID 37873862, 2023). "In humans, LRP6 mutations and its high expression have been detected in several types of cancers, including non-small-cell lung, bladder, breast, and colorectal cancers." (PMID 35052459, 2022). "Three LRP6 missense variants were identified in patients with early colorectal cancer, and these variants were predicted to be pathogenic and to increase Wnt signalling activity in vitro." (PMID 35052459, 2022). "Polymorphisms in the LRP6 gene are also associated with different susceptibility to developing specific types of lung, bladder and colorectal cancers." (PMID 31412666, 2019). "Importantly, although HCT116 are colorectal cancer cells that harbor an activating mutation in β-catenin, they respond to Wnt ligands by LRP6 activation and increased proliferation, making them a suitable model for studying cyclin Y biology." (PMID 34571979, 2021). "It should be noted that the regulation of LRP6 on F-actin dynamics was observed only during neural tube closure and colorectal cancer progression." (PMID 36694134, 2023). "This study aims to determine the effect of CGA in proliferation and apoptosis on two colorectal cancer cell lines and its interactions with β-catenin and LRP6 to elucidate a possible modulatory mechanism of CGA on CRC in the context of Wnt/β-catenin pathway." (PMID 37259421, 2023). "We also found a decrease in LRP6 levels upon knockdown of USP46 in the colorectal cancer cell line, DLD1." (PMID 37798301, 2023). "In colorectal cancer cells, gain of function mutations in KRAS increase LRP6 phosphorylation, resulting in activation of Wnt/β-catenin signaling." (PMID 34589484, 2021). "VSTM2A interacts with the extracellular domain of LRP6 and inhibits LRP6 phosphorylation, thereby inducing its lysosomal degradation, and suppressing colorectal cancer progression." (PMID 34589484, 2021). "Recent reports reveal that LRP6 contributed to tumor progression in colorectal cancer and some other cancers." (PMID 29312635, 2017). "Low density lipoprotein (LDL) receptor-related protein-6 (LRP6) is an important co-receptor of Wnt pathway, which plays a predominant role in development and progression of colorectal cancer." (PMID 29312635, 2017). "In present study, we revealed that phosphorylation of LRP6 was aberrantly upregulated in colorectal carcinoma correlating with TNM or Dukes staging and worse prognosis." (PMID 29312635, 2017). "Immuno-staining of both LRP6 and phosphorylated LRP6 (p-LRP6) were performed in colorectal carcinoma tissue." (PMID 29312635, 2017). "In conclusion, we found active form of LRP6--phosphorylated LRP6 was markedly up-regulate and indicated poor prognosis in colorectal carcinoma." (PMID 29312635, 2017). "Phosphorylation or overexpression of LRP6 contributed to colorectal carcinoma migration and invasion, which arise the question about how LRP6 manage to control such aggressive behavior." (PMID 29312635, 2017). "In this study, we demonstrated that phosphorylated LRP6 was markedly up-regulate in colorectal carcinoma and indicated poor prognosis." (PMID 29312635, 2017). "Future studies are required to address the importance of LRP6 in colorectal cancer development and progression." (PMID 22195040, 2011). "The overexpression or activation of LRP6 could increase Wnt/β-catenin signaling in colorectal cancer cells, which promotes the metastasis of tumor cells in vitro." (PMID 37175248, 2023). "In addition to breast, liver, and colorectal cancer, the role of LRP6 in other cancers has been studied." (PMID 34589484, 2021).
colorectal cancer (continued). "Because initiation of most colorectal cancers (CRC) is often due to activating mutations in Wnt/β-catenin signaling, we verified the role of LRP6 in ApcMin/+ mice, which are heterozygous for an Apc mutation frequently found in human CRC, and which spontaneously develop intestinal adenomas." (PMID 34359960, 2021). "LRP6 phosphorylation was also found to be enhanced in colorectal cancer tissue from patients." (PMID 34589484, 2021). "In colorectal cancer, elevated activity of LRP6 has been reported." (PMID 34589484, 2021). "A bispecific antibody against LRP6, blocking its stimulation in the presence of Wnt and R-spondin ligands, has been shown to delay tumor growth in vivo in a patient-derived xenograft model of colorectal cancer." (PMID 29854300, 2018). "Another recent study identified two novel candidate genes for early-onset colorectal cancer susceptibility: the tyrosine phosphatase PTP-PEST, encoded by PTPN12, a regulator of cell motility; and LRP6, a component of the WNT-F2D-LRP6 complex that triggers WNT signaling." (PMID 29652830, 2018). "Further research efforts in identifying potential drug targets to disrupt LRP6 cytoskeleton modulation could provide a novel therapeutic strategy to improve metastatic colorectal cancer treatment." (PMID 29312635, 2017). "Recently, dysregulation of LRP6 has proved to be involved in the progression of cancers, but its biological role and clinical significance in colorectal cancer remain unclear." (PMID 29312635, 2017). "The data demonstrated that activation of LRP6 could increase Wnt signaling activity in colorectal cancer cells." (PMID 29312635, 2017). "The investigation suggests that LRP6 may be a potential prognostic marker and therapeutic target in the progression of colorectal cancers." (PMID 29312635, 2017). "We therefore analyzed the function of LRP6 in regulating cytoskeletal remodeling and stability that may responsible for colorectal carcinoma migration and invasion." (PMID 29312635, 2017). "However, loss of LRP6 did not affect tumorigenesis in ApcMin/+ mice nor growth of human colorectal cancer cells." (PMID 34359960, 2021). "However, the mechanism about LRP6 in colorectal cancers is seldom investigated." (PMID 29312635, 2017). "This study aims to determine the biological effect of chlorogenic acid (CGA) on two colorectal cancer cell lines, HT-29 and SW480, and its interactions with β-catenin and LRP6 to elucidate a possible modulatory mechanism on the Wnt/β-catenin pathway." (PMID 37259421, 2023). "Lysine catabolism generates Acetyl-CoA necessary for LDL receptor-related protein 6 (LRP6) acetylation that in turn leads to Wnt signalling, which promotes self-renewal of colorectal cancer tumour cells that colonise the liver." (PMID 33915900, 2021). "In contrast, by inhibiting the expression of LRP6, miR-195 can downregulate the β-catenin signaling pathway and the transcription of target genes such as RUNX2 and VEGFa, which consequently reduces the metastasis of colorectal cancer." (PMID 37175248, 2023).
atherosclerosis (23 papers, 2014 to 2025). A disease characterized by the build-up of fatty material and calcium deposition in the arterial wall resulting in partial or complete occlusion of the arterial lumen. "Downregulation of LRP6 activity promotes multiple risk factors for atherosclerosis, including decreased serum LDL, glucose, and triglyceride levels." (PMID 40176913, 2025). "Clinical and genomic trials have also shown that LRP6 genetic variants promote atherosclerosis development." (PMID 40176913, 2025). "The impaired endothelium associated with the LRP6 Y418H mutation increases the risks of developing atherosclerosis in coronary arteries." (PMID 38397878, 2024). "Recently, a reduction in Wnt-mediated transcription resulting from mutations in LRP6 has been confirmed to lead to several features of metabolic syndrome, including atherosclerosis, diabetes, hyperlipidemia, and hypertension, but not obesity." (PMID 37139333, 2023). "In human, LRP6 overexpression and mutations have been reported in multiple complex diseases including hypertension, atherosclerosis, and cancers." (PMID 35052459, 2022). "It has been well known that mutation or dysregulation of LRP6 proteins is directly associated with oxidative stress, dyslipidemia, atherosclerosis, and coronary artery disease." (PMID 35082967, 2022). "Considering the close relationship of LRP6, DCM, and atherosclerosis, we analyzed the association of LRP6 with the mortality endpoints in different etiologies of CHF." (PMID 35187114, 2021). "The discovery of LRP6 mutation in humans provided the first evidence for the critical role of Wnt signaling in atherosclerosis and metabolic syndrome." (PMID 33969358, 2021). "Since the discovery of this mutation, the general role of LRP6 in lipid homeostasis, glucose metabolism, and atherosclerosis has been thoroughly researched." (PMID 26046396, 2015). "Mutations in the Wnt co-receptor LRP6 are associated with high cholesterol levels and elevated concentrations of triglycerides and glucose during fasting, thus providing a basis for the development of atherosclerosis." (PMID 38397878, 2024). "Similarly, LRP6 deficiency on the membrane of bone marrow mesenchymal stem cells(MSCs) restrains the development into the osteoblastic lineage, contributing to atherosclerosis-related bone loss." (PMID 36694134, 2023). "Furthermore, clinical studies and genomic analysis have confirmed that LRP6 genetic variants contribute to the progression of hypertension, atherosclerosis, hypercholesterolemia, and other diseases." (PMID 35052459, 2022). "Importantly, LRP6 overexpression and mutation has been detected in several types of disease, including hypertension, atherosclerosis, hypercholesterolemia, and cancer." (PMID 35052459, 2022). "The first evidence linking Wnt signaling to atherosclerosis came from a discovery of a single gene mutation in the LRP6 gene in a multiplex family with early onset CAD and myocardial infarction, type 2 diabetes, hyperlipidemia and hypertension and later in several nuclear families." (PMID 33969358, 2021). "It has been demonstrated that mutant LRP6 was associated with atherosclerosis." (PMID 35187114, 2021). "Thus, LRP6 functions as a receptor and molecular target of oxPLs for their adverse effect on MSCs, revealing a potential mechanism underlying atherosclerosis-associated bone loss." (PMID 30038821, 2018). "Therefore, these components of the WNT and LRP6 signaling cascade may be potential diagnostic biomarkers of stenosing atherosclerosis." (PMID 38139440, 2023). "After the initial discovery of the LRP6 mutation, the role of LRP6 in CAD and atherosclerosis has rapidly begun to investigate." (PMID 26046396, 2015). "Common genetic variants of LRP6 and TCF4 have been associated with the risks for hyperlipidemia, atherosclerosis, and diabetes in the general population." (PMID 26046396, 2015).